G6PD (glucose-6-phosphate dehydrogenase)
Diseases named in the same sentence as G6PD in open-access papers (continued):
Sharing a sentence is not in itself a finding about the gene and the disease.
G6PD deficiency (continued). "Despite widespread use, mesalamine compounds have been reported to be unsafe in moderate to severe glucose-6-phosphate dehydrogenase (G6PD) deficiency by some Regulatory agencies and patient associations." (PMID 37510911, 2023). "MB is contraindicated in patients with glucose-6-phosphate dehydrogenase (G6PD) deficiency and Heinz body anemia." (PMID 37189570, 2023). "Performance estimates for the STANDARD G6PD Test were calculated by applying a single set of thresholds for G6PD deficiency and female intermediate activity in U/g Hb, as indicated by the manufacturer’s IFU." (PMID 37824592, 2023). "The STANDARD G6PD Test (SD Biosensor, Republic of Korea) is a quantitative enzymatic colorimetric assay intended to aid in the detection of G6PD deficiency at the POC." (PMID 37824592, 2023). "Quantitative spectrophotometry is the standard method for testing G6PD enzyme activity and the definitive diagnosis of G6PD deficiency." (PMID 37127600, 2023). "Favism is a hemolytic disease due to the ingestion of fava beans in individuals with glucose-6-phosphate dehydrogenase (G6PD) deficiency." (PMID 36678214, 2023). "In South Sumatra, the G6PD activity of the six patients diagnosed with G6PD deficiency by FST ranged from 1.4 to 52%; their genotypes were Viangchan (3 hemizygotes), Orissa (1 hemizygote), Chatham (1 heterozygote) and Vanua Lava (1 heterozygote)." (PMID 37672548, 2023). "Given the high prevalence of G6PD deficiency and the widespread practice of henna application, we recommend avoiding it, especially in infancy, until the G6PD status is known." (PMID 36879691, 2023). "Because primaquine cannot be used in patients with glucose-6-phosphate dehydrogenase (G6PD) deficiency, quantitative G6PD activity assays confirmed that all patients had normal enzyme activity." (PMID 37676839, 2023). "Glucose-6-phosphate dehydrogenase deficiency (G6PD) is recognized as the most common enzyme disorder globally, impacting over 400 million individuals." (PMID 38229803, 2023). "In fact, the STANDARD G6PD Test tends toward overestimation of G6PD deficiency at the deficient and intermediate thresholds as compared to the reference assay." (PMID 37824592, 2023). "It is important to note that rasburicase is contraindicated in patients with glucose-6-phosphate dehydrogenase (G6PD) deficiency and should be replaced by allopurinol." (PMID 38118420, 2023). "Infants and children with G6PD deficiency are more vulnerable to serious adverse effects; kidney failure, severe brain damage, and even death have been reported for G6PD-deficient children after exposure to known triggers." (PMID 38132231, 2023). "The aim of this study is to develop multiplex HRM assays that enable a high-throughput platform for detecting G6PD mutations and identifying zygosity, and to determine the prevalence and molecular characteristics of G6PD deficiency among Thai females." (PMID 37967096, 2023). "Evaluated factors included GA, birth weight, bilirubin levels, glucose-6-phosphate dehydrogenase (G6PD) deficiency, and feeding type, with phototherapy given as per AAP guidelines." (PMID 38002910, 2023). "G6PD deficiency: Additionally, primaquine drug, which targets hypnozoites can potentially cause haemolysis in individuals who are G6PD deficient." (PMID 38259757, 2023). "Primaquine prevents relapses of Plasmodium vivax malaria but can cause severe hemolysis in patients with glucose-6-phosphate dehydrogenase (G6PD) deficiency." (PMID 36509054, 2023). "As prompt surveillance and effective treatments are rolled out, preventing primaquine toxicity in the patients having glucose-6-phosphate dehydrogenase (G6PD) deficiency should be a priority for the vivax elimination program." (PMID 38259757, 2023). "Glucose-6-phosphate dehydrogenase (G6PD) deficiency is an X-linked enzymatic disorder that is particularly prevalent in Africa, Asia, and the Middle East." (PMID 37753082, 2023).
G6PD deficiency (continued). "On the other hand, females are less likely to develop G6PD deficiency because, for females, there are two copies of the G6PD gene, and mutation in both copies (homozygous) can lead to G6PD deficiency." (PMID 37892786, 2023). "Fifty patients with P. vivax malaria and glucose-6-phosphate dehydrogenase (G6PD) deficiency were given the WHO-recommended, primaquine regimen of 0.75 mg/kg body weight once per week for 8 weeks." (PMID 37672548, 2023). "Favism is a hemolytic disease due to the ingestion of fava beans in subjects with glucose-6-phosphate dehydrogenase (G6PD) deficiency." (PMID 36678214, 2023). "In India, G6PD testing is rarely performed at health facilities coupled with poor adherence to PQ-based 14-day regimen treatment and high prevalence of G6PD deficiency (e.g., Odisha)." (PMID 37927870, 2023). "Out of the 268 cases of G6PD deficiency tested for G6PD mutations, reverse dot blot identified 20 different G6PD variants." (PMID 38264207, 2023). "In the northern region, parents associating family history with G6PD were 75% less likely to have a child with G6PD deficiency, indicating that this belief reduces the likelihood of G6PD deficiency in their children." (PMID 38229803, 2023). "The Mediterranean mutation (NM_001360016.2(G6PD): c.563C>T (p.Ser188Phe)) was responsible for most cases of G6PD deficiency (20 hemizygous males, 3 homozygous and 16 heterozygous females)." (PMID 37508669, 2023). "Whilst well tolerated in most recipients, 8-AQs can cause severe haemolysis in individuals with the common enzymopathy glucose-6-phosphate dehydrogenase (G6PD) deficiency, necessitating G6PD testing to reduce this risk and guide radical cure." (PMID 37242320, 2023). "As evidence of the increased diagnoses of ADHD among G6PD-deficient individuals, the rates of physician visits were significantly higher among subjects with G6PD deficiency than the matched controls." (PMID 38068806, 2023). "Glucose 6-phosphate dehydrogenase (G6PD) deficiency increases the risk of neonatal hyperbilirubinemia." (PMID 37492600, 2023). "A total of 8459 subjects underwent the G6PD enzyme assay, and the prevalence of G6PD deficiency was found to be 7.54% in males and 3.42% in females in our study cohort." (PMID 38264207, 2023). "Like primaquine, it is contra-indicated for individuals with glucose-6-phosphate dehydrogenase (G6PD) deficiency and requires quantification of G6PD prior to prescribing." (PMID 37764921, 2023). "Testing for G6PD is an essential next step in such cases, as starting methylene blue in G6PD deficiency can worsen hemolysis." (PMID 36938163, 2023). "Participation in G6PD-related educational events significantly associate (adjOR 2.71) with an elevated G6PD deficiency likelihood, primarily among Western region parents." (PMID 38229803, 2023). "Further justification for universal neonatal G6PD screening was the association between G6PD deficiency and significant NHB, including the increased risk associated with borderline intermediate G6PD activities in female infants." (PMID 37508669, 2023). "Regulatory agencies have listed mesalamine as an unsafe drug in subjects with glucose-6-phosphate dehydrogenase (G6PD) deficiency based on the risk of hemolysis, although scientific evidence is lacking." (PMID 37510911, 2023). "To define the clinical and laboratory findings of HIHA in G6PD deficiency, we conducted a literature review for all reported pediatric cases of henna application effects in G6PD-deficient patients." (PMID 36879691, 2023). "Glucose-6-phosphate dehydrogenase (G6PD) deficiency is prevalent in the African American population." (PMID 38132231, 2023). "In the present study, we investigated the recent information on the utilization of the G6PD test and the prevalence of decreased G6PD activity according to different criteria for assessing G6PD deficiency." (PMID 37176619, 2023).
G6PD deficiency (continued). "We hereby describe a G6PD variant in a 15-year-old man known for G6PD deficiency with undetectable activity, corresponding, therefore, to a Class A (previously Class I) CNSHA variant." (PMID 38066190, 2023). "Glucose-6-phosphate dehydrogenase (G6PD) deficiency is a common genetic disorder that affects more than 500 million people worldwide." (PMID 38085718, 2023). "Primaquine (PQ) kills Plasmodium vivax hypnozoites but can cause severe hemolysis in patients with glucose-6-phosphate dehydrogenase (G6PD) deficiency." (PMID 37604475, 2023). "The identification of G6PD deficiency as a risk factor provides the opportunity for physicians to make early diagnoses based on G6PD status and to establish appropriate therapy." (PMID 36768075, 2023). "Being aware of the need to increase fluid intake during a G6PD attack is associated with a higher likelihood (adjOR 1.53) of G6PD deficiency in offspring, with particular significance observed in the Western region (adjOR 2.69)." (PMID 38229803, 2023). "As part of the study, the prevalence of G6PD deficiency was estimated for this township and it can also be applicable for considering routine G6PD testing in the national malaria surveillance system in the future." (PMID 37045879, 2023). "We investigated as a contributing factor the possibility of G6PD-linked anemia owing to the known risk following SP exposure, but the A- allele of G6PD deficiency was present in only 2 of these 7 children." (PMID 36215323, 2022). "In many countries, the utilization of PQ is hindered by the widespread prevalence of glucose-6-phosphate dehydrogenase (G6PD) deficiency, which is common in malaria-endemic areas." (PMID 35392979, 2022). "G6PD deficiency polymorphisms such as G6PD-202 G > A were 0.022, 0.032 and 0.018 in SM, UM and CTR groups, respectively." (PMID 35811813, 2022). "The research on G6PD deficiency and its role in cancer began in 1965 when Beaconsfield was studying the relationship between areas and G6PD deficiency and G6PD-related cancer." (PMID 35207558, 2022). "Glucose-6-phosphate dehydrogenase (G6PD) deficiency is a potentially dangerous enzymopathy that affects more than 400 million people worldwide." (PMID 35287717, 2022). "Noteworthily, participants with defective G6PD deficiency generally had higher serum ferritin levels compared to G6PD normal individual." (PMID 35103063, 2022). "G6PD deficiency is one of the most common X-linked enzymopathies caused by G6PD gene variants, and G6PD deficiency is a common genetic disease in China." (PMID 36204111, 2022). "This study presents a case where a 16-year-old male with glucose-6-phosphate dehydrogenase (G6PD) deficiency presented with severe nodulocystic acne after three weeks of isotretinoin therapy." (PMID 35371846, 2022). "In Thailand, the prevalence of G6PD deficiency ranges between 5% and 34%, and more than 20 G6PD variants have been identified." (PMID 36508454, 2022). "We concluded that for the diagnosis of G6PD deficiency in male infants, evaluating G6PD activity had better performance than targeted genotyping." (PMID 36212124, 2022). "G6PD genotyping should also be used to confirm G6PD status, especially in female individuals suspected of having G6PD deficiency." (PMID 36339627, 2022). "The results of G6PD deficiency from quantitative MR and flow cytometry were compared with G6PD mutation results from multiplex ARMS-PCR/direct DNA sequencing." (PMID 35840819, 2022). "In conclusion, our study highlights that an individual’s G6PD activity is significantly higher during acute malaria, particularly those with intermediate or severe G6PD deficiency." (PMID 35544453, 2022). "In populations with a high prevalence of G6PD deficiency, it is advisable to assess G6PD in potential blood donors, according to the WHO guidelines." (PMID 36431166, 2022).
G6PD deficiency (continued). "Congenital Hypothyroidism (CH), Cystic Fibrosis, Glucose-6-phosphate dehydrogenase (G6PD) deficiency, and ProfoundBiotinidase deficiency (BD) are common disorders in India." (PMID 37701517, 2022). "G6PD activity distributions spanned the widely used thresholds to demarcate classes for G6PD deficiency, supporting the updated classification schema recently proposed during a WHO-convened meeting of international experts." (PMID 36145477, 2022). "G6PD deficiency is a genetic disorder caused by mutation in the G6PD gene affecting G6PD deficiency in all cell types, including reticulocytes." (PMID 36419023, 2022). "Moderate to high prevalence of G6PD deficiency and malaria warrants G6PD testing before treating with primaquine (PQ) for radical cure of Plasmodium vivax." (PMID 36384674, 2022). "Because the G6PD gene is located on chromosome X, the clinical signs are mainly present in hemizygous males and homozygous females when G6PD deficiency patients are exposed to oxidative inducing agents or infections." (PMID 36248708, 2022). "In this study, we looked studied the distribution of different G6PD gene variants, the prevalence of G6PD deficiency, and the relationship between genotypes and phenotypes related to enzyme function in Baise, Guangxi Zhuang Autonomous Region." (PMID 36704359, 2022). "The prevalence of G6PD deficiency was examined in 1,125 people by using a quantitative G6PD activity assay based on water-soluble tetrazolium salts (WST-8)." (PMID 36339627, 2022). "The 8-aminoquinoline class of drugs, including primaquine and tafenoquine, is haemolytic in subjects with glucose-6-phosphate dehydrogenase (G6PD) deficiency." (PMID 38406309, 2022). "Glucose-6-phosphate dehydrogenase (G6PD) deficiency, and beta thalassemia- and sickle-cell disease inducing mutations, prevalent in Africa and the Mediterranean, are all linked to malaria resistance." (PMID 36547255, 2022). "Glucose-6-phosphate dehydrogenase (G6PD) deficiency is a common X-linked genetic trait, and thus affects mainly males." (PMID 36339224, 2022). "Glucose-6-phosphate dehydrogenase (G6PD) deficiency represents a barrier to the full deployment of anti-malarial drugs for vivax malaria elimination and of first-line antibiotics." (PMID 38406309, 2022). "Another study showed that hypoxia-induced PH was prevented by G6PD deficiency, and that established severe PH in Cyp2c44−/− mice was ameliorated by the knockdown with G6PD shRNA or by G6PD inhibition." (PMID 35712711, 2022). "A quantitative G6PD enzymatic activity assay based on a spectrophotometric technique is the reference assay to detect G6PD deficiency and G6PD intermediates." (PMID 36419023, 2022). "Multiplexed HRM assays revealed a G6PD deficiency frequency of 22.40% (252/1,125) in the studied population, with G6PD Mahidol being the most common variant, accounting for 99.60% of the detected mutations." (PMID 36339627, 2022). "The results from genetic tests were categorized as G6PD normal or G6PD deficiency within both female and male samples for the purpose of identifying the optimal cut-off values of %bright cells from ROC curve analysis." (PMID 35840819, 2022). "The patient was screened in Sichuan Provincial People’s Hospital at birth and found to have decreased G6PD enzyme activity and diagnosed with G6PD deficiency." (PMID 36160421, 2022). "Mutations other than class-I and class-II causing G6PD deficiency are away from the structural domain of G6PD protein." (PMID 35368337, 2022). "Of 45 patients with G6PD deficiency and intermediate G6PD, 19 patients (42.2%) were infected with P. falciparum, 25 patients (55.6%) were infected with P. vivax, and 1 patient (2.2%) was coinfected with P. falciparum and P. vivax." (PMID 36038921, 2022). "Dabrafenib can cause hemolytic anemia in patients who have G6PD deficiency and it is known that there are geographic differences worldwide in percent of patients who are G6PD deficient." (PMID 36212431, 2022).
G6PD deficiency (continued). "The univariate analysis revealed that haemoglobin levels were significantly associated with both G6PD deficiency/G6PD normal (p < 0.001) and G6PD MahidolG487A/ G6PD Wildtype (p < 0.001)." (PMID 36038921, 2022). "G6PD deficiency was present in 2.1% of China’s population overall, and over 35 different G6PD gene mutations were known, with G6PD Kaiping and G6PD Canton predominating in earlier investigations." (PMID 36704359, 2022). "With a worldwide prevalence of approximately 500 million people affected, glucose-6-phosphate-dehydrogenase (G6PD) deficiency is an inherited enzymatic disorder causing hemolytic anemia." (PMID 35743352, 2022). "MeBlu is contraindicated in persons taking serotonin reuptake inhibitors or having hereditary glucose-6-phosphate dehydrogenase (G6PD) deficiency." (PMID 35631447, 2022). "In this study, we found four G6PD gene mutations in the 18 T1D with G6PD deficiency children: c.1376G > T, c.1388G > A, c.95A > G, and c.871G > A, the most frequent G6PD pathogenic variants in Guangdong." (PMID 35313968, 2022). "Mutations in the G6PD gene result in an x-linked hereditary disease known as G6PD deficiency, which is associated with the protein variants having different levels of enzyme activity leading to a wide variety of biochemical and clinical phenotypes." (PMID 35368337, 2022). "On the other hand, the African G6PD A- variant is the mildest of all the G6PD deficiency variants; thus it is relatively resistant to primaquine-induced hemolysis." (PMID 35216617, 2022). "There have been reports of more than 400 G6PD variants, of which approximately 50% of variants lead to G6PD deficiency characterized by reduced enzyme activity and structural integrity of the protein structure." (PMID 36381187, 2022). "EDTA-blood samples were collected for a hematological parameters study, G6PD deficiency screening, and a molecular study for G6PD mutation." (PMID 36248708, 2022). "A quantitative spectrophotometric assay is suitable to quantify newborn G6PD activity and detect G6PD deficiency in the prevention of hemolytic anemia of G6PD deficiency." (PMID 36419023, 2022). "To provide more information to diagnose this disorder, we performed this study to carry out the prevalence of G6PD deficiency and G6PD variants in the Vietnamese population by direct sequencing." (PMID 35845714, 2022). "The diagnosis of G6PD deficiency and molecular genotyping of G6PD in malaria patients prior to PQ and TQ administration are necessary to prevent adverse outcomes." (PMID 36038921, 2022). "The training covered P. v and relapses; radical cure with primaquine; G6PD deficiency and the risk of haemolysis; and G6PD testing." (PMID 36264996, 2022). "Various cases of haemolysis and methaemoglobinaemia were described in patients with glucose-6-phosphate dehydrogenase (G6PD) deficiency treated with HCQ or CQ for COVID-19." (PMID 35631460, 2022). "Another three (2.5%) neonates were reported to have anomalies, namely bilateral clubfoot minor, glucose-6-phosphate dehydrogenase (G6PD) deficiency, and also sacral dimple." (PMID 35677772, 2022). "Available data support that a single low-dose (SLD) of primaquine administered with ACT is efficacious for reducing transmission of mature P. falciparum gametocytes, and is also safe even in glucose-6-phosphate dehydrogenase (G6PD) deficiency." (PMID 35279143, 2022). "We report 21 novel X chromosome loci, including an LDL-lowering locus involving a missense variant in G6PD, known to cause G6PD deficiency (p.V68M)." (PMID 36575460, 2022). "According to the reported causes of acquired G6PD deficiency in the literature, a test indicating a G6PD activity below the normal range requires carefully ruling out a false positive test." (PMID 36431166, 2022). "G6PD deficiency is caused by loss-of-function mutations in the G6PD gene and follows an X-linked recessive inheritance pattern." (PMID 35685917, 2022).